TXLNGY (taxilin gamma Y-linked (pseudogene))
Synonyms: formerly CYorf15A; CYorf15B; TXLNG2P
Gene: Transcribed unprocessed pseudogene on chromosome Y (19,567,382 to 19,604,120, forward strand). Ensembl gene ENSG00000131002.
Diseases named in the same sentence as TXLNGY in open-access papers:
TXLNGY is named in the same sentence as 7 diseases in open-access papers, as found by Europe PMC text mining. Sharing a sentence is not in itself a finding about the gene and the disease. The quoted sentences say what the papers report.
atherosclerosis (1 paper, 2023). A disease characterized by the build-up of fatty material and calcium deposition in the arterial wall resulting in partial or complete occlusion of the arterial lumen. "The present study identifies genes already classified in the atherosclerosis process as genes that codify for encoding cellular adhesion molecules (NLGN4Y), cellular exocytosis (TXLNGY), induction of IFN-α (DDX3Y), cellular apoptosis (EF1AY), and prevention of protein degradation (USP9Y)." (PMID 36831031, 2023).
cryptorchidism (1 paper, 2019). The failure of one or both testes of a male fetus to descend from the abdomen into the scrotum during the late part of pregnancy. "Our findings implicate Y-chromosomal genes, including USP9Y, UTY, TXLNGY, RBMY1B, RBMY1E, RBMY1J and TSPY4, some of which are known to be important for spermatogenesis, in the curative hormonal treatment of cryptorchidism-induced infertility." (PMID 31171972, 2019).
glaucoma (1 paper, 2023). Increased pressure in the eyeball due to obstruction of the outflow of aqueous humor. "Database analysis revealed that seven host genes (NEAT1, SAMD12, KDM5D, ZFY, EIF1AY, TXLNGY, and DDX3Y) of nine DEcircRNAs were also differentially expressed in blood samples of patients with glaucoma, and the trend of differential expression of circRNAs and host genes was consistent." (PMID 37805546, 2023).
lung carcinoma (1 paper, 2023). "One study found that downregulation of TXLNGY and Y disruption in the tumour are associated with poor prognosis in male-dominant cancers such as lung cancer." (PMID 37509410, 2023).
TXLNGY also shares sentences with these, for which no sentence is quoted: tumour (2 papers); cancer (1); Infertility (1).